PIK3CA (phosphatidylinositol-4,5-bisphosphate 3-kinase catalytic subunit alpha)
Diseases named in the same sentence as PIK3CA in open-access papers (continued):
Sharing a sentence is not in itself a finding about the gene and the disease.
cancer (continued). "One region at 3q26 found to be increased in copy number in approximately 40% of ovarian and others cancers contains PIK3CA, which encodes the p110α catalytic subunit of PI3K." (PMID 19384426, 2007). "The PIK3CA mutations described in cancer constitutively activate p110α and, when expressed in cells drive oncogenic transformation." (PMID 19384426, 2007). "By combining the copious amount of sequencing data over the past year, we find that the PIK3CA gene is mutated on average in 15% of human cancers, although there is obviously great variability in the tissue type, that is, colon vs breast vs lung." (PMID 16449998, 2006). "Breast and lung cancers had a relatively low rate of PIK3CA mutations (8 and 4% respectively), although the sample size of all cancer types was relatively small (n=12–24) with the exception of colorectal cancers (n=234)." (PMID 16449998, 2006). "Gene amplifications, deletions and more recently, somatic missense mutations in the PIK3CA gene have been reported in many human cancer types including cancers of the colon, breast, brain, liver, stomach and lung." (PMID 16449998, 2006). "Upregulation of AKT by mutation of PTEN (a tumour suppressor gene that antagonises AKT pathway) or amplification PIK3CA (encodes catalytic subunit of PI3-K) were reported in a number of human cancers including breast carcinoma." (PMID 16288304, 2005). "By contrast, isoform-specific PI3K inhibitors demonstrate higher efficacy and reduced adverse events by selectively inhibiting individual isoforms and most isoform-specific inhibitors are directed against the p110α catalytic subunit, which is frequently mutated in cancer by PIK3CA mutations." (PMID 41301038, 2025). "Novel research data in different cancer types indicate that mutations within PIK3CA might serve as a biomarker of an improved response to immune therapy." (PMID 41096755, 2025). "PIK3CA mutations promote the proliferation and invasion of human cancer cells." (PMID 40050490, 2025). "In addition, ARID1A, BRAF, and PIK3CA mutations seemed to increase in the metastatic cohort, compared with TCGA and in-house primary cancer cohorts (all p < 0.05)." (PMID 39941707, 2025). "Interestingly, despite the fact that these same PIK3CA mutations are one of the most common oncogenic mutations in cancer, vascular malformation associated with PIK3CA mutation rarely acquire a malignant phenotype." (PMID 41430313, 2025). "Furthermore, somatic mutations in PIK3CA confer several advantages to cancer cells, including induced cell growth, stimulated angiogenesis, increased invasion, and resistance to antiestrogen therapy." (PMID 41049266, 2025). "Furthermore, a 2013 study assessing twenty signaling pathways across twelve major cancer types found that 52.2% of EC samples harbored PIK3CA mutations, 30.9% had PIK3R1 mutations, and 63.5% had PTEN mutations." (PMID 41262902, 2025). "PIK3CA activating mutations are among the most common PI3K/Akt pathway alterations in cancer." (PMID 40508087, 2025). "PIK3CA is one of the most commonly mutated oncogenes in human cancers." (PMID 40148314, 2025). "In this review, we outline therapeutic targets in PI3K/AKT/MTOR signaling in solid tumors, the current state of using inhibitors of this pathway to treat patients whose cancers possess activating mutations in PIK3CA, AKT1/2, or MTOR, and exciting new inhibitors that are entering clinical trials." (PMID 40564038, 2025). "PIK3CA mutations result in constitutive activation of this pathway, leading to increased cell proliferation, survival, and angiogenesis, which are hallmarks of cancer." (PMID 39858102, 2025). "This class of PI3Ks is commonly found mutated in cancers, particularly p110α/PIK3CA." (PMID 40386392, 2025).
cancer (continued). "Similarly, six of the nine instances of RNA VAF repeatedly classifying BoostDM drivers as passenger mutations involved the gene PIK3CA (i.e., this happened separately across six cancer types)." (PMID 40514689, 2025). "The identification of PIK3CA H1047R mutation's impact on immunotherapy responsiveness underscores the need to further investigate oncogene‐driven immune evasion mechanisms to improve cancer treatment outcomes." (PMID 40740483, 2025). "Recent studies reported that hotspot PIK3CA mutations can be immunogenic and could represent an attractive target for T cell-based cancer immunotherapies." (PMID 41410746, 2025). "Co-occurrence of ARID1A and PIK3CA mutations are frequently observed in various cancers." (PMID 40761291, 2025). "Finally, we analyzed the association of CDH1 and PIK3CA with specific biological processes at pan-cancer level." (PMID 41404730, 2025). "Various cancers have demonstrated mutations or amplifications in the PIK3CA gene." (PMID 40740483, 2025). "Mutation in the PIK3CA gene can lead to the excessive activation of the signaling pathway, promoting glucose uptake and glycolysis to provide the energy and biosynthetic substances necessary for cancer cell growth." (PMID 39744225, 2025). "Breast pleomorphic adenocarcinoma may be a low-grade malignant tumor and may be spared from aggressive post-operative treatment even though the PIK3CA gene mutation can be identified in patients." (PMID 41040523, 2025). "In addition, this study describes one TCR against the PIK3CAE545K mutant gene product, one of the most frequent PIK3CA mutations that represents 23% of all PIK3CA mutations and is expressed by 2.8% of all patients with advanced cancer." (PMID 41410746, 2025). "Given the complexity of the PI3K pathway within the broader network of signaling cascades, it is expected that PIK3CA mutations may exert paradoxical effects in different oncogenic contexts, even within the same type of cancer." (PMID 40508087, 2025). "Firstly, PIK3CA mutations arm cancer cells with the immune checkpoint regulator programmed death-ligand 1 (PD-L1), which transmits an inhibitory signal and reduces the proliferation of antigen-specific CD8+ T cells through binding to programmed cell death protein 1 (PD-1)." (PMID 39717717, 2025). "In addition to metabolism, cancer cells harboring PIK3CA mutations domesticate immune cells directly through secreting growth factors, cytokines, and chemokines." (PMID 39717717, 2025). "Additionally, PIK3CA is one of the most commonly mutated oncogenes in human cancers, and PIK3CA mutations have been shown to be a favorable factor for the clinical outcomes of PI3K inhibitors." (PMID 40148314, 2025). "Besides, PIK3CA mutations occur in various cancers, at frequencies of 5% to 8% in NSCLC cases and approximately 6.33% in Chinese pan-cancer samples." (PMID 41189942, 2025). "The PIK3CA gene, which encodes the p110α, is the most frequently mutated oncogene in cancer." (PMID 39717717, 2025). "However, the combination therapy was more effective in cancers bearing PIK3CA mutations than in cancers with PTEN loss." (PMID 39920872, 2025). "In NPC, combination therapies targeting PIK3CA and its co-mutated partners might be an avenue for improved outcomes, as mutations in PIK3CA, particularly hotspot variants like H1047R, are often linked to therapy resistance and poor outcomes in other cancers." (PMID 40361470, 2025). "Additionally, the progression-free survival (time before the cancer worsened) was nearly double that in the PIK3CA-mutated group, at 9.1 months compared to 4.7 months." (PMID 40050490, 2025).
cancer (continued). "This co-application approach may be particularly relevant for patients with activating mutations in PIK3CA (~30% in a variety of cancers) as it could overcome the resistance associated with these mutations." (PMID 40148314, 2025). "AKT inhibition may be particularly effective in tumors with both PTEN loss and PIK3CA mutations, as these cancers often demonstrate AKT pathway hyperactivation." (PMID 40072110, 2025). "The PIK3CA gene is also mutated in 18% of breast cancers, 39% of endometrial and 9% of non-small cell lung cancer, highlighting it as a key therapeutic focus for cancer treatment across almost all types." (PMID 40386392, 2025). "Alpelisib is a PI3K pathway inhibitor that is often used in cancers with PIK3CA mutations." (PMID 39685105, 2024). "However, recent studies have also identified the potential for an uncoupling of AKT activity from PIK3CA mutations in some cancers." (PMID 38954770, 2024). "In conclusion, our study demonstrated that the combination of alpelisib 300 mg daily and capecitabine 1,250 mg/m2 twice daily for 14 days in 3-weekly cycles is a safe and well-tolerated treatment option for patients with advanced cancers harboring PIK3CA mutations." (PMID 39070139, 2024). "Therefore, AutoEpiCollect’s pan-cancer epitope-based vaccine design is predicted to elicit a strong, sustained immune response in patients with PIK3CA-mutated cancer cells." (PMID 38671743, 2024). "PIK3CA, which encodes the p110α catalytic subunit, is frequently mutated in various cancers and is known to be associated with cell signaling, proliferation, invasion, and cancer development." (PMID 38927493, 2024). "The higher frequency of somatic PTEN mutations in combination with PIK3CA copy number gain at chromosome 3q26 for SClow as compared to SChigh HNSCC suggested an inverse association between PI3K pathway activity in cancer cells and peripheral nerve abundance in the TME." (PMID 38920662, 2024). "PIK3CA is a common oncogene that encodes the p110α catalytic subunit of class I phosphatidylinositol-3-kinases (PI3Ks), namely PI3Kp110α, which is involved in cancer driving mechanisms mainly as an upstream signal for AKT." (PMID 39113889, 2024). "However, for patients with a family history of cancer or patients aged younger than 59 years, PIK3CA mutation was shown to be significantly associated with a shorter overall prognosis." (PMID 38616230, 2024). "This suggests that the role of PIK3CA mutation as a driver mutation may vary depending on the cancer type." (PMID 39070139, 2024). "Therefore, alteration to the PIK3R1 SH2 domain or its interactions with PIK3CA would be consistent with the effects of the cancer hotspot mutations of PIK3CA." (PMID 38541623, 2024). "This study reveals that multi‐PIK3CA mutations, found in 10.3% of PIK3CA‐mutant tumors across a broad pan‐cancer cohort, display a unique pattern of cis/trans‐orientations, with a notable distinction in the helical domain where mutations occur predominantly in trans." (PMID 39054873, 2024). "We hypothesized that the frequency and patterns of multi‐PIK3CA mutations vary significantly across different cancer types and that these variations likely correlate with distinct clinical features or prognoses." (PMID 39054873, 2024). "However, exogenously introduced KRAS G13D in the PIK3CA-mutated cancer cell leads to drug resistance." (PMID 39056802, 2024). "By analyzing ctDNA, we seek to elucidate whether the PIK3CA (H1047R) mutations can serve as reliable biomarkers for cancer detection and monitoring in dogs, thereby offering insights into the potential of liquid biopsy marker in CMTs." (PMID 39462049, 2024).
cancer (continued). "The dysregulation of this pathway has been implicated as a pivotal driver in 30% of cancers, with mechanisms involving activating mutations in PIK3CA, loss of function mutations in PTEN, excessive activation of upstream molecules, and gain-of-function mutations as well as amplification of AKT." (PMID 39582546, 2024). "An extensive panel of cancer cell lines was used for an in vitro pharmacologic sensitivity screen, and the results showed that sensitivity to alpelisib was positively correlated with the presence of the PIK3CA mutation, amplification, or copy number increase." (PMID 39062182, 2024). "However, cancer cells can have increased PAM pathway activity due to factors other than canonical PIK3CA and PTEN mutations." (PMID 38839777, 2024). "Mutations in PIK3CA are among the most frequent in a number of cancer types." (PMID 37612583, 2024). "Moreover, cancer cell lines harboring PTEN loss or mutant PIK3CA required a higher drug concentration to establish 50% growth inhibition (IC50) in 2D cultures compared to that needed to inhibit AKT kinase activity." (PMID 39614261, 2024). "Co-mutations accompanying PIK3CA mutations may amplify the impact of PIK3CA variations on cancer progression, making them significant from a clinical management perspective." (PMID 39685930, 2024). "PIK3CA is mutated in approximately 30–40% of all human cancers." (PMID 38832948, 2024). "HPV-associated cancers exhibit a recurrent somatic mutation at two helical domain hotspots in the oncogenic driver gene PIK3CA, which is involved in the regulation of cell growth, proliferation, differentiation, glucose metabolism, protein synthesis and apoptosis." (PMID 38535531, 2024). "AKT1 mutations are much less common than PIK3CA mutations among childhood cancers." (PMID 39510293, 2024). "In different types of cancer, PIK3CA gene mutations are often observed, which may influence both the activity level of the PI3K/Akt pathway and the expression profile of the analyzed genes." (PMID 38891994, 2024). "The treatment of canine cancer may benefit from the development of novel human cancer drugs that target shared oncogenic mutations, such as alpelisib for metastatic breast cancer with PIK3CA mutations." (PMID 39462049, 2024). "Thus, BRCA mutation status influences the ability of mutant PIK3CA to alter the differentiation pathway of breast epithelial cells and potentially influence metastatic properties of cancer cells." (PMID 38059556, 2024). "Given the enhanced responsiveness to PI3K inhibitors in breast cancer with multi‐PIK3CA mutations, we also explored the potential for similar responses in other cancer types, which could suggest broader applications for these inhibitors." (PMID 39054873, 2024). "Moreover, the PIK3CA gene that encodes the catalytic subunit p110α is one of the frequently mutated oncogenes in various human cancers." (PMID 38339127, 2024). "The molecular characterization of an entire spectrum of slow-flow vascular malformations revealed the presence of well-known oncogenic driver mutations in PIK3CA that cause cancer in other tissues and drive venous and lymphatic malformations in the endothelium." (PMID 38747293, 2024). "PIK3CA, the gene encoding phosphoinositide 3-kinase alpha (PI3Kα), known for its pivotal role in numerous cellular processes, stands out due to its high mutation frequency in diverse cancer types." (PMID 38832948, 2024). "The contribution of PIK3CA mutations to cancer phenotype is distinct from other oncogenic drivers." (PMID 38612902, 2024). "In addition to RAS family members, other genes commonly found to be mutated in other cancers, such as PIK3CA, are also found altered in some percentage of BC, having an impact on their characteristics and prognosis." (PMID 38987766, 2024). "Moreover, overexpression of PIK3CA gene has been associated with lymph node metastasis in different cancers, including colorectal and gastric cancers." (PMID 38336976, 2024).
cancer (continued). "This correlation suggests that immunotherapy may be particularly effective in PIK3CA-mutated cancers, although more research is needed to fully understand this interaction." (PMID 39555098, 2024). "PIK3CA is commonly mutated and amplified in various cancer types." (PMID 38655260, 2024). "We found a significantly higher PIK3CA mutation rate in in H2L than in HER2-positive carcinomas." (PMID 38893129, 2024). "Additionally, PIK3CA mutations suppress the differentiation of luminal and basal mammary cells, resulting in more cancer cell lineages." (PMID 36671478, 2023). "In an additional large phase I trial of 166 patients with PIK3CA-mutated cancer, the ORR was 9%." (PMID 36900211, 2023). "However, the frequency of PIK3CA mutations differs among populations and varies among cancer types, stages and ethnicity." (PMID 37195967, 2023). "Mutation of the PIP3‐producing PIK3CA, in contrast, is a frequent event in a number of cancers." (PMID 37577760, 2023). "This shared genetic similarity between tumors and vascular anomalies suggests that as benign tumors, VeMs might have similar genetic underpins as cancers caused by the exact same somatic PIK3CA GOF mutations." (PMID 37109059, 2023). "Regardless of the precise molecular explanation, an analogy can be drawn with the mutational spectrum of the PIK3CA gene in breast, head/neck, cervical, and others cancers, which has two prominent APOBEC3 mutation hotspots (E542K, E545K) and no obvious hairpin structures." (PMID 38033156, 2023). "The PIK3CA gene is one of the most frequently mutated genes in all of human cancer." (PMID 36635288, 2023). "The cancer subtype where we have the most data concerning PIK3CA mutations is BC." (PMID 36934165, 2023). "Based on the identified somatic pathogenic variants, anti-cancer drugs such as PIK3CA or MEK inhibitors could be applied as therapy, i. e., PIK3CA inhibition is clinically effective without substantial side effects in patients with PROS." (PMID 38835734, 2023). "This PI3K inhibitor exhibits potential as a targeted therapy for dogs with PIK3CA mutations: in vitro effects demonstrated its capacity to inhibit cancer cell migration, suppress AKT phosphorylation, thereby inhibiting cell proliferation, and induce apoptosis through caspase-3/7 activation." (PMID 37368773, 2023). "Our findings offer a mechanistic interpretation for PTEN and PIK3CA mutations frequently observed in cancer and NDD samples, which may form the basis for functional and detailed structural analysis, including molecular dynamics simulations." (PMID 37925498, 2023). "Although PIK3CA mutation could induce PD‐L1 expression on cancer cells, it has also been reported to induce a suppressive TIME, a critical barrier for the success of cancer immunotherapy." (PMID 37965796, 2023). "Other cancer types accounted for 28 patients (21.5%) and 28 PIK3CA mutations (20.7%)." (PMID 36934165, 2023). "Cancer genome analysis using next-generation sequencing (NGS) technologies involves sequencing and analyzing the DNA of cancer cells to identify genetic mutations known as hot-spot regions (such as KRAS and PIK3CA) that are associated with the development and progression of cancer." (PMID 37598236, 2023). "Mutations in PIK3CA are mostly identified in coding domains of P110α, a major hotspot, although different domains might be mutated according to the origin of the cancer." (PMID 37368773, 2023). "Mut_44 (Pik3ca Δ6) corresponds to a T1025A modification in the catalytic domain of phosphatidylinositol 3-kinase—recently identified as a novel driver mutation in addition to the dominant H1047R affecting the same domain in human cancers." (PMID 37655661, 2023).